RNVU1-2 (RNA, variant U1 small nuclear 2)
Synonyms: vU1.2; RNU1-71; U1P1; U1.1; vU1.11; U1P2A; RNU1-12P; RNU1-13P; RNU1P2; RNU1P6; RNVU1-11
Gene: Small nuclear RNA gene on chromosome 1 (148,388,490 to 148,388,651, reverse strand). Ensembl gene ENSG00000238825.
Gene Ontology:
Molecular function: pre-mRNA 5'-splice site binding
Biological process: mRNA 5'-splice site recognition
Cellular component: U1 snRNP
Homologues: Orthologues: mouse Gm23330 (91% identical). Paralogues in human: RNU1-1 (96% identical), RNU1-2 (96% identical), RNU1-27P (96% identical), RNU1-28P (96% identical), RNU1-3 (96% identical), RNU1-4 (96% identical), RNVU1-18 (96% identical), RNVU1-29 (96% identical), U1 (96% identical), RNVU1-28 (95% identical), RNVU1-7 (95% identical), RNVU1-31 (94% identical), and 133 more.